SNORD100 (small nucleolar RNA, C/D box 100)
Synonyms: HBII-429
Gene: Small nucleolar RNA gene on chromosome 6 (132,816,802 to 132,816,877, forward strand). Ensembl gene ENSG00000221500.
Gene Ontology:
Biological process: RNA processing
Cellular component: nucleolus
Homologues: Orthologues: macaque SNORD100 (99% identical), chimpanzee SNORD100 (97% identical), pig SNORD100 (95% identical), guinea pig SNORD100 (92% identical), rabbit SNORD100 (92% identical), rat Snord100 (87% identical), tropical clawed frog SNORD100 (87% identical), mouse Snord100 (82% identical).